NSUN2 (NOP2/Sun RNA methyltransferase 2)
Diseases named in the same sentence as NSUN2 in open-access papers (continued):
Sharing a sentence is not in itself a finding about the gene and the disease.
tumor (continued). "NSUN2 was more highly expressed in tumor tissues than in adjacent normal tissues." (PMID 34504059, 2021). "Both tumor number and tumor size of Nsun2+/− mice were smaller than those of Nsun2+/+ mice." (PMID 34345012, 2021). "In addition, the tumor immune microenvironment is affected by NSUN2 and NSUN6 through multiple pathways, such as the regulation of RNA metabolism, the cell cycle and immune cell activation." (PMID 34512153, 2021). "whereas, overexpression of NSUN2 significantly promoted tumor growth in nude mice." (PMID 32332707, 2020). "However, the mechanisms of NSun2-mediated mRNA methylation in tumor development remain to be further studied." (PMID 33093178, 2020). "Furthermore, our presented findings suggest that NSUN2 promotes tumor growth and metastasis by increasing ALYREF/YBX1-mediated YAP expression in NSCLC and effective inhibition of m5C modification might provide a potential treatment strategy for NSCLC." (PMID 41794778, 2026). "NSUN2 also regulates immune-related pathways, further promoting drug resistance and immune evasion, indicating that targeting NSUN2 and its downstream pathways may provide novel strategies to overcome tumor resistance." (PMID 41256859, 2025). "Moreover, among all BMDM subgroups, tumor size in the siNSUN2 group is smallest, and tumor size in the siNSUN2-siSOCS3 group and the NC group don’t have a significant difference, indicating that knock-down of NSUN2 inhibited tumor growth in vivo while SOCS3 rescued this inhibition." (PMID 41354740, 2025). "Collectively, these findings establish NSUN2 as a critical epitranscriptomic hub linking tumor metabolism and immune regulation, and suggest that co-targeting NSUN2-mediated m5C pathways and metabolic or immune checkpoints may represent a promising strategy for overcoming therapy resistance." (PMID 41256859, 2025). "Therefore, a comprehensive understanding of NSUN2’s functions and mechanisms in tumor biology and immune regulation is crucial, as it not only elucidates the molecular basis of tumorigenesis but also provides a theoretical foundation for cancer diagnosis, prognostic evaluation, and targeted therapy." (PMID 41256859, 2025). "Additionally, NSUN2 enhances migration, invasion, and tumor growth in vivo." (PMID 41463199, 2025). "Moreover, NSUN2 overexpression compromised the shNONO-induced tumor burden." (PMID 40033337, 2025). "Additionally, effective tumor-specific delivery of NSUN2 inhibitor remains a significant challenge." (PMID 40083919, 2025). "Additionally, transcriptome analysis indicates that NSUN2 might reduce immune cell infiltration in the tumor microenvironment and contribute to chemotherapy resistance." (PMID 39695216, 2024). "Interestingly, the expression level of NSUN2 was higher in tumour vs. matched normal tissues." (PMID 38468490, 2024). "Mediated by methyltransferases (such as NSUN2), m5C modification affects mRNA stability, translation efficiency, and nuclear export, promotes the expression of oncogenes and immune-related genes, and enhances the proliferation, migration, and invasion of tumor cells." (PMID 39867908, 2024). "Moreover, NSUN2 functions as a glucose sensor, ensuring mRNA stability of three prime repair exonuclease 2 during glucose deficiency, thereby inhibiting the GAS/STING pathway, sustaining tumor development, and conferring resistance to immune therapy." (PMID 39164641, 2024). "In cells, the expression of P57 and NSUN2 were negatively correlated, and the high expression of NSUN2 reduced the stability of mRNA, inhibited the expression of P57, and promoted the proliferation of tumor cells by catalyzing m5C methylation in the 3′UTR region of P57 mRNA." (PMID 37168511, 2023). "In addition, tumour‐specific NSUN2 expression was noted in RB samples and cell lines." (PMID 37228185, 2023).
tumor (continued). "Moreover, we employed reverse transcription qPCR (RT–qPCR), immunohistochemistry (IHC) and western blot assays to detect the expression of NSUN2 in the normal and OS tumor tissues we collected from Wuhan University Zhongnan Hospital and the Affiliated Tumor Hospital of Zhengzhou University." (PMID 36792587, 2023). "The results suggested that NSUN2, working as a methyltransferase of m5C, may act on the expression of downstream target genes together with other modified regulators, thus playing critical roles in tumor progression." (PMID 37769000, 2023). "In addition, some studies have shown that the NSUN2 has the properties of delaying protein synthesis and controlling the stem cell cycle in stem cells, which may lead to tumor recurrence and chemotherapy resistance." (PMID 36335189, 2022). "Moreover, NSUN2 may participate in regulating tumor progression through multiple mechanisms, which needs more research to explore." (PMID 32978516, 2020). "It seems that H19 may not be the best target for the function of NSUN2 in tumor which NSUN2 deficiency significantly inhibited cancer cell proliferation and migration." (PMID 32978516, 2020). "Pharmacologic disruption of NSUN2-ALYREF-MALAT1 signaling restores sorafenib sensitivity, positioning this pathway as an actionable target for overcoming TKI-tolerant tumor cells." (PMID 41362736, 2026). "NSUN2 is upregulated in multiple CRC mouse models and human tumours, and its depletion impairs ISC expansion and hyperproliferation, leading to reduced tumour initiation." (PMID 41856980, 2026). "Histological and multiplex immunofluorescence analyses confirmed that NSUN2 deletion reduced tumor-induced PNI and downregulated CDCP1 and STC1, while lactate supplementation increased pan-lactylation, NSUN2, CDCP1, and STC1 expression." (PMID 41356184, 2026). "NOP2, NSUN2, and NSUN4, key RNA m5C methyltransferases, are highly expressed in NSCLC tumour tissue, and their levels are strongly correlated with tumour grade, tumour size, and poor outcomes." (PMID 40860147, 2025). "m5C pathways (NSUN2–ALYREF) can stabilize growth factor and EGFR–STAT3 transcripts and have been linked to pro-tumor signaling and immune evasion in hepatocellular carcinoma; whether these changes directly rewire tumor angiogenesis or cytokine secretion in vivo at scale is still being clarified." (PMID 41280938, 2025). "In turn, NSUN2 enhances the stability of GLUT1 mRNA, the primary glucose transporter in tumor cells, thereby promoting increased glucose uptake." (PMID 40765828, 2025). "Functional studies reveal that NSUN2 stabilizes NEO1 mRNA, thereby promoting cell proliferation, migration, and invasion, while also reprogramming tumor glycolytic metabolism and histone lactylation levels." (PMID 41256859, 2025). "NSUN2 is significantly overexpressed in OSCC tissues and cell lines and its high expression correlates with poor prognosis and aggressive tumor characteristics." (PMID 41436732, 2025). "For example, FOXC2-AS1 increases the m5C methylation level of FOXC2 mRNA by recruiting NSUN2, which is further recognized by YBX1 and regulates the proliferation, migration, and invasion of tumour cells." (PMID 40860147, 2025). "In contrast, NSUN2 stabilizes ENO1 mRNA via m5C modification, enhancing glycolysis and lactate production and thereby promoting tumor stemness in CRC." (PMID 40859309, 2025). "NSUN2 enhances PKM2 mRNA stability by increasing m5C levels at the C773 site of its 3’-UTR, thereby promoting tumor metabolism and proliferation." (PMID 41256859, 2025). "NSUN2-catalyzed mRNA methylation of TREX2, TIAM2, PFAS, and ORAI2 promotes the oncoprotein expression and tumor progression, mainly through enhancing the mRNA stability of these oncogenes." (PMID 40033337, 2025). "By sustaining TREX2 expression, NSUN2 limits cytosolic dsDNA accumulation and suppresses cGAS/STING-mediated innate immune responses, thereby facilitating tumor progression and resistance to anti-PD-L1 therapy." (PMID 41256859, 2025).
tumor (continued). "Mechanistically, in TNBC, both NSUN2 and NSUN6 play critical roles in tumourigenicity and the tumour immune microenvironment." (PMID 40008496, 2025). "Targeting the NSUN2/SLC7A11 axis can inhibit in vivo and in vitro tumor growth in EC cells by promoting lipid peroxidation and ferroptosis." (PMID 40370440, 2025). "The proto-oncogene heparin-binding growth factor (HDGF) mRNA is methylated by NSUN2, and YBX1 stabilizes HDGF mRNA by binding to m5C methylation sites and recruiting ELAVL1, thereby promoting tumor development." (PMID 40370440, 2025). "In OS, NSUN2 up-regulates FABP5 expression and stabilizes its mRNA, thereby promoting fatty acid metabolism in OS cells and driving tumor progression." (PMID 41256854, 2025). "Moreover, increasing evidence indicates that NSUN2 may influence tumor immune evasion and the response to immunotherapy by regulating the expression of immune-related molecules, modulating immune cell functions, and shaping the tumor microenvironment." (PMID 41256859, 2025). "To elucidate the mechanism by which NSUN2 promotes NPC via m5C modification, we initially collected 16 confirmed tumor suppressor genes and 27 potential tumor suppressor genes." (PMID 41463199, 2025). "For example, inhibiting NSUN2 in PDAC reduces stromal fibrosis and restores ductal epithelial differentiation, thus slowing tumor progression and reinforcing NSUN2’s potential as a therapeutic target." (PMID 40114967, 2025). "UMAP-based expression overlays revealed that NSUN2, YTHDC1, ALKBH5, ZC3H13, and TRDMT1 were predominantly expressed within epithelial clusters, consistent with a tumor-intrinsic regulatory role." (PMID 40565233, 2025). "Extracellular vesicles derived from DLBCL cells promoted the transfer of NSUN2 to DLBCL cells, promoting tumor cell proliferation, M2 macrophage polarization, and immune escape, while inhibiting apoptosis." (PMID 41462962, 2025). "NSUN2, functioning as a writer for m5C, emerges as a direct target of MYC, a renowned modulator of tumour cell proliferation, initially identified for its upregulation in malignant skin tumours." (PMID 40008496, 2025). "Collectively, these in vivo results validate our in vitro findings, underscoring the critical role of the NSUN2-SQSTM1/P62 axis in regulating autophagy and ferroptosis to promote OSCC tumor growth." (PMID 41436732, 2025). "NSUN2 recruits the histone methyltransferase EZH2 to epigenetically silence the tumor suppressor PRDM11, thereby promoting BCa cell proliferation and tumor progression." (PMID 41256859, 2025). "NSUN2 modifies the 3’-UTR of TEA domain transcription factor 1 (TEAD1) mRNA through m5C, promoting TEAD1 expression and thereby enhancing tumor cell proliferation and invasion." (PMID 40370440, 2025). "Within cancer tissues, the heightened expression of NSUN2 and YBX1, functioning as the ‘writer’ and ‘reader’ of m5C, respectively, contributes to tumour formation by upholding mRNA stability." (PMID 40008496, 2025). "A glucose metabolism advantage drives NSUN2 upregulation in tumor cells, which stabilizes key glycolytic gene transcripts (GLUT1, HK2, PFKM) via mRNA methylation, enhancing tumor cells’ competitive advantage in glucose uptake." (PMID 41256859, 2025). "Specifically, NSUN2 can stabilize the mRNAs of PD-L1, FSP1, and other immunosuppressive factors, enhancing the immunosuppressive capacity of tumor cells, leading to impaired CD8+ T cell function and the establishment of an immunosuppressive TME." (PMID 41256859, 2025). "The glucose/NSUN2/TREX2 axis drives tumorigenesis and resistance to PD-L1 immune therapy in immune-competent syngeneic tumor mouse models by suppressing the cGAS/STING pathway, apoptosis, and CD8+ T cell infiltration." (PMID 40370440, 2025).
tumor (continued). "ROC curve analysis has highlighted NSUN6’s considerable diagnostic value across different cohorts Silencing NSUN2 significantly reduces the stemness of CRC cells, and its knockdown effectively impairs tumor growth and metastasis to the liver and lungs in vivo." (PMID 40114967, 2025). "In vivo, NSUN2 and SQSTM1/P62 expression was positively correlated, according to IF analysis of tumor sections." (PMID 41436732, 2025). "We establish that TTPAL promotes tumor initiation and progression through m5C-mediated stabilization of SREBP2 mRNA, executed via its interaction with the methyltransferase NSUN2." (PMID 40713894, 2025). "The NSUN2‐overexpressing HCT‐116 cells showed more obvious metastatic ability and formed more tumour foci than the control HCT‐116 cells, as shown by the photon number and haematoxylin–eosin (H&E) staining." (PMID 40156167, 2025). "For example, elevated NSUN2 expression in ATC cells enhances the translation of key transcription factors and antiapoptotic genes, promoting tumor progression and drug resistance." (PMID 40819127, 2025). "Emerging work in immuno-oncology links the NSUN2–ALYREF axis to PD-L1 upregulation and immune evasion, highlighting RNA-modification circuitry as a tractable point of intervention in the tumor–immune dialogue." (PMID 41280938, 2025). "The m5C modification, controlled by factors such as NSUN2, TET2, and YBX1, also affects tumor immune responses by altering immune cell infiltration and the expression of immune checkpoints." (PMID 39695216, 2024). "Here we identified that NSUN2, a key RNA m5C methyltransferase, is highly expressed in NSCLC tumor tissue." (PMID 38403250, 2024). "Among the differentially expressed genes present, DNMT1, NSUN2, NSUN4, and TET2 were highly expressed in LNM + tumor tissues while NSUN5 and NSUN7 expression was reduced." (PMID 37907576, 2023). "In this study, we initially demonstrated that NSUN2 is necessary for PFAS activation by enhancing its RNA stability in RB, which expands the current understanding of dynamic m5C function during tumour progression." (PMID 37228185, 2023). "Therefore, NSUN2 may play oncogenic roles in multiple tumor types." (PMID 37769000, 2023). "The m5C RNA methylation regulators NSUN2 and NSUN6 were predictors of survival and affected the progression and tumor immune microenvironment in TNBC." (PMID 35721510, 2022). "The protein expressions of METTL1, NSUN2, EIF4G3, LARP1, NCBP1, and NCBP2 were higher in tumor tissues than in normal tissues; however, the protein expressions of WDR4, EIF4E1B, and NCBP2L were negative in both tumor and normal tissues." (PMID 35785179, 2022). "For instance, combined knockdown of NSUN2 and METTL1, which catalyses tRNA 7-methylguanosine, has shown to sensitize tumour cells to the chemotherapeutic agent 5’-fluorouracil (5-FU), confirming the link between RNA methylation, cell survival and chemotherapy." (PMID 35205419, 2022). "The activation of the NSUN2/YBX1/HDGF axis was proven to promote cell growth, tumor progression and metastasis." (PMID 34512153, 2021). "IHC assays showed sequential upregulation of NSUN2 protein in normal esophageal epithelium, atypical hyperplasia lesions and ESCC tumor tissues." (PMID 34345012, 2021). "The m5C writer NSUN2 is a direct target of MYC, a well-known regulator of tumour cell proliferation, which was first found upregulated in malignant skin tumours." (PMID 34638933, 2021). "Conversely, NSUN2 depletion or treatment with an NSUN2 small-molecule inhibitor suppressed PANC-1 cell invasion and migration, reduced neurite outgrowth in neuronal cells, and diminished the capacity of tumor cells to invade DRG and promote neurite extension." (PMID 41356184, 2026). "Moreover, NSUN2 is transcriptionally activated by the YAP-TEAD2 complex, forming a positive feedback loop that promotes tumor growth and metastasis, a process effectively suppressed by m5C inhibitors both in vivo and in vitro." (PMID 41794778, 2026).
tumor (continued). "Based on this mechanism, combined targeting of the GLUT1/NSUN2 axis with the small molecule inhibitor WZB117 and PD-L1 immune checkpoint blockade synergistically suppresses tumor evolution and reverses immune suppression, offering a potential strategy for therapy-resistant HCC." (PMID 41256859, 2025). "Additionally, NSUN2 knockdown inhibits AML cell proliferation and clonogenicity while promoting apoptosis; in mouse AML models, NSUN2 silencing reduces tumor burden and prolongs survival." (PMID 41256859, 2025). "To evaluate the function of NSUN2 in CRC progression in vivo, we subcutaneously injected stable NSUN2‐overexpressing HCT‐116 cells into nude mice to establish mouse xenograft models and monitored the growth of the resulting tumours." (PMID 40156167, 2025). "A dual-targeting strategy combining GLUT1/NSUN2 axis inhibitor WZB117 with PD-L1 blockade, which synergistically suppressed tumor evolution and reversed immunosuppression in preclinical models, suggesting a novel synergistic therapeutic strategy for treatment-resistant HCC." (PMID 41373022, 2025). "NSUN2 also promotes GC progression through an alternative mechanism by inhibiting m5C methylation in the 3′-UTR of p57Kip2 to reduces mRNA stability and expression, thereby preventing G1/G0 arrest and promoting tumor progression." (PMID 41413017, 2025). "Furthermore, NSUN2 promotes SLC7A11 mRNA stability via the recognition role of YBX1, which resists the ferroptosis pathway of tumour cells to promote survival." (PMID 40860147, 2025). "Furthermore, the NSUN2/PGK1 axis activates the PI3K/AKT signaling pathway, further promoting tumor progression." (PMID 41256859, 2025). "Interestingly, lactate accumulation in tumour cells, in turn, activates NSUN2 transcription via histone H3K18 lactylation (H3K18la) and induces NSUN2 lactylation at residue Lys356 (K356), which is essential for target RNA capture." (PMID 40860147, 2025). "Furthermore, in vivo studies confirmed the role of NSUN2 in promoting HCC immune escape and tumor formation by regulating the m5C modification of SOAT2." (PMID 41462962, 2025). "NSUN2 also enhances m5C modifications on three prime repair exonuclease 2 mRNA, promoting its expression, inhibiting cGAS/STING activation, and facilitating tumor development." (PMID 41463199, 2025). "NSUN2 lactylation enhances m5C methylation and stabilizes GCLC mRNA, thereby promoting glutathione (GSH) synthesis, reducing lipid peroxidation, and conferring ferroptosis resistance in tumor cells." (PMID 40859309, 2025). "NSUN2-mediated RNA methylation promotes H19 lncRNA expression, with methylated H19 interacting with the oncoprotein G3BP1 to delay MYC mRNA decay, thereby driving tumor progression." (PMID 40114967, 2025). "NSUN2 also works with YBX1 synergistically, m5C modification of the mRNA of the glycolytic enzyme ENO1 enhances glycolysis and lactate production, forming a positive feedback loop that promotes tumor progression." (PMID 39867908, 2024). "Additionally, we used immunohistochemistry (IHC) and Western blot assays to detect NSUN2 expression in normal and NSCLC tumor tissues collected from The First Affiliated Hospital of Zhengzhou University." (PMID 38403250, 2024). "Furthermore, high NSUN2 expression in ATC cells enhances the translation of key transcription factors and anti‐apoptosis related genes to promote tumour progression and resistance." (PMID 37983928, 2023).